TFAP2A (transcription factor AP-2 alpha)
Diseases named in the same sentence as TFAP2A in open-access papers (continued):
Sharing a sentence is not in itself a finding about the gene and the disease.
melanoma (34 papers, 2000 to 2025). A malignant, usually aggressive tumor composed of atypical, neoplastic melanocytes. "Among the clonal SNVs, we observe hotspot coding mutations, such as Kras (G12D) and Gnaq (Q209L) that are well-known cancer drivers, and variants in Sf3b1 and Tfap2a, which are frequently mutated genes in melanoma." (PMID 40950124, 2025). "TFAP2A encodes Activating Protein 2 Alpha (AP-2α), which facilitates melanoma metastasis through the transcriptional activation of genes within the E2F pathway, which inhibits apoptosis." (PMID 38732371, 2024). "The enriched motifs of the TFAP2 family can most likely be linked to TFAP2A because this is a master regulator in human melanocytes and melanoma." (PMID 32732264, 2020). "Altogether these findings suggest that the gene encoding AP-2α (TFAP2A) acts as a tumour suppressor in melanoma." (PMID 10864211, 2000). "We detected clonal mutations of all types that affected genes known to contribute to melanoma initiation, including hotspot SNVs in Kras and Gnaq, SNVs in frequently mutated sites of Sf3b1 and Tfap2a, homozygous deletion of Cdkn2a, and amplifications of Met, Braf, Mitf, Kras, Cdk4, and Erbb3." (PMID 40950124, 2025). "However, reduced TFAP2A expression is associated with poor prognosis in gastric cancer, and the loss of TFAP2A is linked with melanoma through the regulation of cell adhesion molecules." (PMID 33713277, 2021). "Specifically, loss of TFAP2A expression is associated with progression of human melanoma." (PMID 24023917, 2013). "Loss of TFAP2A expression is associated with progression of human melanoma." (PMID 24023917, 2013). "Furthermore, the TFAP2A–MCAM network is reported to be associated with melanoma metastasis." (PMID 35625787, 2022). "PAX3 is known to drive expression of genes involved in both an invasive and proliferative phenotype in melanoma, and TFAP2A can work as a rheostat switch between phenotypic groups." (PMID 40428399, 2025). "In the same vein, TFAP2A was also shown to counteract heterochromatin formation and enhance epigenetic activation of the E2F pathway promoters in melanoma cells." (PMID 39994865, 2025). "Transcripts related to melanoma progression and poor prognosis (Sox6, Sox11, Tfap2a, Myo7a) were upregulated in IgG-treated animals." (PMID 38740748, 2024). "In contrast, TFAP2A, a related family member expressed in proliferative melanoma that shares near-identical binding motif with TFAP2B, was negatively correlated with ALDH1A3." (PMID 38963759, 2024). "(but in melanoma, this physical interaction is regulated by hypermethylation of the HRK promoter preventing binding of TFAP2A and synergically with the loss of TFAP2A)." (PMID 37291585, 2023). "In zebrafish melanoma Tfap2a and Tfap2e also appear to act redundantly to promote proliferation and, interestingly, to suppress cell adhesion and cell migration." (PMID 35580127, 2022). "Studies have found a reactivation of an NC program in melanoma, and indeed we observed upregulation of NC genes such as crestin, sox10, tfap2a, dlx2a, among others." (PMID 34791221, 2022). "We performed Gene Set Enrichment Analysis (GSEA) for SOX10 and MITF ChIP-seq in 501mel melanoma line and TFAP2A in human primary melanocytes on the tiles ranked according to their activity." (PMID 34874265, 2021). "Anti-TFAP2A immunoreactivity is strong and concentrated in the nucleus of human primary melanocytes but appears weaker and more diffuse in several melanoma cell lines, consistent with a reduction of TFAP2A RNA levels in melanoma." (PMID 28249010, 2017). "It is notable that TFAP2A levels are decreased in advanced-stage melanoma tumors versus earlier stage melanoma and nevi, whereas MITF expression levels are relatively constant (data from The Cancer Genome Atlas)." (PMID 28249010, 2017). "Further investigation will be necessary to determine the potential tumor-promoting or tumor-inhibiting consequences of TFAP2A expression (or activity) levels in melanoma." (PMID 28249010, 2017).
melanoma (continued). "Of note, several of the other genes with decreased expression upon knockdown of Tfap2a have been reported in the literature as activated (Aldh1a3, Igf2bp1, Ephb2, Pbk) or downregulated (Qpct, Wfdc1) in melanoma." (PMID 28249010, 2017). "These constructs, together with a control vector, were transfected into M21 melanoma cells, which express TFAP2A." (PMID 28249010, 2017). "TFAP2A is a TF involved in melanoma and normal melanocyte function and co-localizes with MITF at promoters involved in pigment cell differentiation in primary human melanocytes (H Seberg, E van Otterloo, and RA Cornell, manuscript in preparation)." (PMID 25803486, 2015). "Treatment of melanoma cells with demethylating agent 5-aza-2′-deoxycytidine (5-Aza) resulted in reduction of miR-638 expression, which was reversed upon TFAP2A knockdown." (PMID 25650662, 2015). "While TFAP2A has been extensively studied in melanoma, our investigations show an as yet unrecognized and understudied role for TFAP2C in this malignancy via its regulation of ECM1 expression." (PMID 24023917, 2013). "TFAP2A derived melanoma metastasis by regulating E2F and EZH2." (PMID 40813717, 2025). "In human melanoma, TFAP2A expression is regulated by its promoter CpG methylation." (PMID 37291585, 2023). "Furthermore, melanomas, squamous cell carcinomas, most skin and breast cancers and a few cervical and urothelial cancers have strong nuclear immunoreactivity for TFAP2A." (PMID 31199790, 2019). "Co-occupancy of enhancers by MITF and TFAP2A was also reported in human melanoma cell lines." (PMID 28249010, 2017). "Defining this contribution may help to explain why TFAP2A expression is reduced in advanced-stage melanoma compared to benign nevi." (PMID 28249010, 2017). "Likewise, it was reported that in 501mel melanoma cells depleted of TFAP2A, the expression levels of MITF were unchanged compared to control cells, while expression of TYR, encoding the rate limiting enzyme of melanin synthesis, was decreased." (PMID 28249010, 2017). "However, melanomas often have reduced TFAP2A expression, accompanied by methylation of the TFAP2A promoter, and so are not ideal systems to study the role of TFAP2A in normal melanocyte development and function." (PMID 28249010, 2017). "The results confirm that TFAP2A frequently co-occupies regulatory elements with MITF, identify genes underlying pigmentation phenotypes in model organisms and patients with TFAP2A mutations, and reveal TFAP2A as a candidate locus to modify diseases associated with MITF, including melanoma." (PMID 28249010, 2017). "Furthermore, enhanced over-expression of TFAP2A in metastatic melanoma cells inhibits tumor progression at cutaneous sites and reduces the formation of lung metastases after intravenous injection." (PMID 24023917, 2013). "While there is evidence that the KIT gene is dependent on direct stimulation by the Transcription Factor Activator Protein 2 alpha (TFAP2A) in melanoma, analyses of mutant model organisms indicate a more complex regulatory scenario within embryonic melanocytes." (PMID 20862309, 2010). "Additionally, TFAP2A prevented the deacetylation activity of the NuRD Complex on E2F pathway promoters by competing with the same chromatin fragments, which drove hyper-acetylation of promoter nucleosomes and facilitated transcription in melanoma." (PMID 38265973, 2024). "Additionally, the abolition of TFAP2A expression in melanoma was confirmed to increase malignancy." (PMID 30824562, 2019). "TFAP2A and TFAP2C are members of the TFAP2 transcription factor family, which plays a crucial role in regulating melanocyte differentiation and melanoma phenotypes." (PMID 40725490, 2025).
melanoma (continued). "The second gene most related to TFAP2A was KDM5B, a histone demethylase which has been proven essential for immune evasion in melanoma." (PMID 38265973, 2024). "For instance, TFAP2A potentiates lung adenocarcinoma metastasis and stimulates angiogenesis in lung cancer cells with acquired resistance to anlotinib; TFAP2A-mediated activation of E2F and EZH2 drives melanoma metastasis." (PMID 38890750, 2024). "To test this model in SK-MEL-28 melanoma cells we deleted the two TFAP2 paralogs with highest expression, TFAP2A and TFAP2C, creating TFAP2 knockout (TFAP2-KO) cells." (PMID 35580127, 2022). "In conclusion, two independent strategies of motif analysis suggest conservation of TF binding sites for known melanoma master regulators, with conserved SOX10, MITF, TFAP2A, and ETS TF family motif enrichment in MEL enhancers across all six studied species." (PMID 32732264, 2020). "In our previous studies, we have found that expression of two SLN genes (PIGR and TFAP2A), when combined with clinicopathological features, correlated with prognosis in SLN-positive melanoma patients." (PMID 33373316, 2020). "This supports a regulatory role for TFAP2A not only in differentiation, but across other categories of genes proposed to be regulated by MITF in melanocytes and melanoma, as with the MITF rheostat." (PMID 28249010, 2017). "As SOX10, YY1, TFAP2A, and ETS1 all have important roles in melanocytes and/or melanoma, the MAREs identified here define a combinatorial signature of TFs critical for gene regulation in this lineage." (PMID 25803486, 2015). "Since ECM1 levels appeared to have an inverse correlation with TFAP2A expression (in contrast to that observed in HMEC’s) and knowledge regarding the role of TFAP2C in melanomas is rather limited, we focused additional investigations on this association." (PMID 24023917, 2013). "Gel shift experiments showed that TFAP2A can bind an element 1.2 kb upstream of the KIT transcription start site, and expression driven by this enhancer in melanoma cells is lost when the TFAP2 binding sites are deleted." (PMID 20862309, 2010). "Abnormalities in TFAP2A, KIT, and MITF expression in melanoma highlight the importance of this pathway in human disease." (PMID 20862309, 2010). "In addition, they suggest that TFAP2A activity, like MITF activity, has the potential to modulate the phenotype of melanoma cells." (PMID 28249010, 2017). "It is known that elimination of TFAP2A from non-metastatic primary melanoma cells increases their malignancy while re-expression abrogates it, by controlling transcription of genes such as MCAM-MUC18, MMP2, PAR1, VEGF, BCL2, CDKN1A/p21, E-cadherin and KIT." (PMID 25650662, 2015). "Studies also show that inactivation of TFAP2A via a dominant negative mechanism augments the tumorigenicity of non-metastatic melanoma cell lines in nude mice." (PMID 24023917, 2013). "In contrast to TFAP2A, there is very limited data regarding the role of TFAP2C in melanoma." (PMID 24023917, 2013). "Studies show that inactivation of TFAP2A via a dominant negative mechanism augments the tumorigenicity of non-metastatic melanoma cell lines in nude mice." (PMID 24023917, 2013). "Thus, early requirements for Tfap2a and its paralog Tfap2c observed in zebrafish neural crest induction may suggest a role for TFAP2 in this invasive subtype of melanoma as well." (PMID 28249010, 2017).
Branchio-oculo-facial syndrome (32 papers, 2010 to 2025). "Not only KBG syndrome but also Townes–Brocks syndrome caused by SALL1 variants and branchio-oculo-facial syndrome (BOFS) caused by TFAP2A variants show pheno-typic overlap with BOR/BO syndrome." (PMID 39125727, 2024). "TFAP2A monoallelic variants are associated to the branchio-oculo-facial syndrome (BOFS; OMIM #113620), characterized by branchial cleft sinus defects, ocular anomalies, and cleft or pseudocleft lip/palate." (PMID 38459225, 2024). "Branchiooculofacial syndrome is a rare developmental defect caused by heterozygous deletions or mutations in the TFAP2A gene." (PMID 37426677, 2023). "With respect to humans, TFAP2A mutations are associated with Branchio-Oculo-Facial Syndrome (MIM, 113620), while TFAP2B is mutated in Char Syndrome (MIM, 169100)." (PMID 35333176, 2022). "Mutations in tfap2a result in Branchio‐oculo‐facial syndrome, characterized by cleft palate‐craniofacial disorder." (PMID 32314458, 2020). "Mutations in TFAP2A cause Branchio-Oculo-Facial Syndrome (BOFS), which is characterized by CL/P, branchial arch defects, and ocular anomalies, and are associated with nonsyndromic CL/P in several populations." (PMID 31122291, 2019). "Rearrangements affecting the genomic interactions between TFAP2A and enhancers active in neural crest cells located in the TFAP2A TAD have recently been implicated in branchio-oculofacial syndrome." (PMID 31801603, 2019). "TFAP2A mutations have been found in patients diagnosed with branchio-oculo-facial syndrome, which is characterized by branchial defects, ocular anomalies and facial defects, including CL/P25." (PMID 28232668, 2017). "In humans, mutations in TF AP-2-alpha (TFAP2A) have been associated with branchio-oculo-facial syndrome (BOFS), a congenital birth defect characterized by craniofacial abnormalities, skin and eye defects as well as hearing problems." (PMID 27176626, 2016). "Given the spectrum of human midfacial anomalies associated with disrupted functions of TFAP2A (branchio-oculo-facial syndrome), TFAP2B (Char syndrome), and ALX1, ALX3 and ALX4 (frontonasal dysplasia), these findings link features of previously disparate disorders into a shared genetic hierarchy." (PMID 38063857, 2024). "Similarly, mutations in human TFAP2A are associated with the Branchio-Oculo-Facial Syndrome with variable ocular anomalies including microphthalmia or anophthalmia, iris and chorioretinal coloboma, strabismus, and cataract." (PMID 25966682, 2015). "For example, transcription factor AP-2 alpha (TFAP2A) lies in 6p24 and has been found to be mutated in patients with branchio-oculo-facial syndrome who present with colobomatous microphthalmia and corneal clouding among other features, suggesting that TFAP2A plays a role in ocular embryogenesis." (PMID 21738392, 2011). "Furthermore, biochemical studies suggest that dominant mutations in TFAP2A or TFAP2B – resulting in branchio-oculo-facial syndrome (MIM: 113620) or Char syndrome (MIM: 169100), respectively – create mutant proteins that may interfere with other TFAP2 paralogs." (PMID 38063857, 2024). "In humans, mutations in TFAP2A have been identified as a cause of branchio-oculo-facial syndrome (BOFS) and are linked to genes such as IGF6, BCOR, and P63, which are known to be connected with orofacial clefting." (PMID 39201474, 2024). "In humans, mutations in TFAP2A have been linked to the developmental defects in the Branchio-Oculo-Facial Syndrome (BOFS)." (PMID 28412966, 2017). "Cervical thymic cysts are painless neck masses that can present suddenly in children, or in association with cutaneous pharyngeal defects and ocular and facial anomalies as in branchio-oculo-facial syndrome (BOFS), an autosomal-dominant transmitted disorder with mutations in the TFAP2A gene." (PMID 34449578, 2021).
Branchio-oculo-facial syndrome (continued). "Importantly, mutations in human TFAP2A and TFAP2B, are also linked to the human conditions Branchio-Oculo-Facial Syndrome and Char Syndrome respectively, conditions which both have a craniofacial component." (PMID 35333176, 2022). "In patients with branchiooculofacial syndrome, an 89Mb inversion was found with a breakpoint located in the TAD, which disconnects the TFAP2A gene from enhancers such as Enh100 and Enh105, leading to haploinsufficient expression of TFAP2A in human neural crest cells." (PMID 37426677, 2023).
lung carcinoma (16 papers, 2015 to 2024). "The expression levels of SIX1 and TFAP2A are specifically increased in HIV-associated lung cancer and are associated with poorly differentiated tumor tissue." (PMID 30177858, 2018). "All these results indicate that the expression levels of SIX1 and TFAP2A are specifically increased in HIV-associated lung cancer." (PMID 30177858, 2018). "However, TFAP2A and TFAP2C is highly expressed in bladder cancer, lung cancer and other tumors, and overexpression of TFAP2A and TFAP2C is associated with poor prognosis of many tumors." (PMID 37859819, 2023). "We found that SIX1, PROM1, and TFAP2A were upregulated in HIV-associated lung cancer." (PMID 30177858, 2018). "Nonetheless, the TFAP2 genes family seems to play an important role in lung cancer pathogenesis, especially the TFAP2A, TFAP2C, and TFAP2D members in LUAD patients." (PMID 36831334, 2023). "In lung cancers, TFAP2A potentiates lung adenocarcinoma metastasis by regulating the miR-16 family/TFAP2A/PSG9/TGF-beta signaling pathway." (PMID 36707053, 2023). "Recent study has shown that TFAP2A can inhibit the proliferation of lung cancer cells while overexpressing TFAP2A can promote tumor metastasis." (PMID 37859819, 2023). "Three genes, TFAP2A, TJP1 and TMEM63B, have been shown to be associated with the B lymphocytes in lymph node metastasis of lung cancer." (PMID 34575089, 2021). "Considering the principal contribution of LUAD towards lung cancer, we tried to explore detailed function of TFAP2A in LUAD." (PMID 33824285, 2021). "TFAP2A- and SIX1- specific staining was clearly observed in the nucleus of the lung cancer cells including HIV associated squamous cell carcinoma (SCC) and AC." (PMID 30177858, 2018). "Several articles on the role of TFAP2A/B/C in lung cancer progression have been published, but the role of TFAP2D/E in this process is still unknown." (PMID 39695171, 2024). "Although several studies have revealed the expression level of TFAP2A and its impact in lung cancer based on single-cell RNA-seq analysis and bioinformatics analysis, TFAP2A may be involved in tumour progression." (PMID 39695171, 2024). "In lung cancer, TFAP2A drives cancer progression through multiple pathways." (PMID 39695171, 2024). "Kaplan‐Meier analysis revealed that high TFAP2A expression might predict poor clinical prognosis in patients with lung cancer." (PMID 38994891, 2024). "The contribution of TFAP2A was found for the malignant progression of lung cancer." (PMID 36016137, 2022). "First, previous study mainly deduced, from lung cancer cell lines cultured in vitro, that TFAP2A could weaken some malignant phenotypes, like proliferation, apoptosis resistance, and chemotherapy insensitivity." (PMID 33824285, 2021). "However, our finding seemed contradictory with previous studies suggesting tumor-inhibition potential of TFAP2A in lung cancer." (PMID 33824285, 2021). "Furthermore, TFAP2A was confirmed to inhibit the development and progression of lung cancer, as well as the disordered pathway of FENDRR (FOXF1 adjacent non-coding development regulatory RNA)." (PMID 32294625, 2020). "Although TFAP2A has not been explicitly reported to be associated with lung cancer, it has been associated with the generation of a variety of tumors." (PMID 26402252, 2015). "The TFAP2A and TFAP2C genes were reported to be involved in tumorigenesis as tumor suppressors in melanomas, breast, gastric, prostate, colorectal, and lung cancer." (PMID 36831334, 2023). "In lung cancer, therefore, the role of TFAP2A has not been clearly clarified and its expression profile, clinical association, biological function and regulatory mechanism still calls for further investigation." (PMID 33824285, 2021).